RNU6-314P (RNA, U6 small nuclear 314, pseudogene)
Gene: Small nuclear RNA gene on chromosome 17 (16,098,704 to 16,098,807, forward strand). Ensembl gene ENSG00000252383.
Homologues: Orthologues: macaque U6 (96% identical), guinea pig U6 (82% identical), mouse Gm24150 (80% identical), guinea pig U6 (70% identical). Paralogues in human: RNU6-1019P (82% identical), RNU6-1060P (82% identical), RNU6-1243P (82% identical), RNU6-203P (82% identical), RNU6-24P (82% identical), RNU6-255P (82% identical), RNU6-543P (82% identical), RNU6-1151P (81% identical), RNU6-166P (81% identical), RNU6-199P (81% identical), RNU6-242P (81% identical), RNU6-41P (81% identical), and 1286 more.